FOXM1 (forkhead box M1)
Diseases named in the same sentence as FOXM1 in open-access papers (continued):
Sharing a sentence is not in itself a finding about the gene and the disease.
cancer (continued). "In our study, we propose that the chr12p13 gain leads to the over-expression of genes annotated in this genomic region (i.e., GAPDH, TPI1, FOXM1) creating cancer-specific metabolic addiction." (PMID 30873387, 2019). "The role of AURKA, PLK1 and FOXM1 in cancer pathogenesis and progression arises from their interaction with β-catenin, which is a central signal for normal and CML stem cells." (PMID 31122263, 2019). "Several studies reported the overexpression of FOXM1 stimulates the proliferation of tumor cells during the progression of NSCLC and other types of cancers and also associated with poor overall survival." (PMID 31681566, 2019). "HIF-1 directly binds to the FOXM1 promoter and upregulates the expression of FOXM1, and downstream target genes mediate cancer cell proliferation under hypoxic conditions." (PMID 30992007, 2019). "A pan-cancer study found FOXM1 is overexpressed across all studied 32 TCGA cancer types including NSCLC compared to normal tissues." (PMID 31681566, 2019). "FOXO3 and FOXM1 are members of the forkhead box transcription factor family which play opposite roles in tumorigenesis, drug resistance and cancer progression." (PMID 31727006, 2019). "Noteworthy, several studies have also demonstrated a positive correlation between increased FoxM1 levels and poor cancer prognosis endowing cancer cells with over-proliferative capacities." (PMID 30795536, 2019). "Taken together, our findings support a novel partnering role of EPS8 with FOXM1 in the regulation of cancer cell proliferation and provides interesting insight into future design of therapeutic strategy to inhibit cancer cell proliferation." (PMID 30941306, 2019). "Forkhead box protein M1 (FOXM1) is another important transcription factor that plays an important role in cancer development and progression." (PMID 31146503, 2019). "The high expression level and role of FOXM1 in MB and other cancer types make it an interesting and suitable target for clinical intervention." (PMID 31541075, 2019). "The FOXM1 transcription factor plays vital roles in cancer initiation, progression, metastasis, DNA damage repair, and resistance to apoptosis." (PMID 30728402, 2019). "Among the three FOXM1 isoforms, FOXM1c showed the highest expression in normal and tumor tissues and cancer cell lines." (PMID 30795624, 2019). "FOXM1 expression is elevated in most human cancers and plays a crucial role in human carcinogenesis." (PMID 30782607, 2019). "It has been shown that the impaired activation of several receptor tyrosine kinases, such as RTK, RAF, RAS and MAPK2, in cancer cells has led to the nuclear accumulation of FOXM1, via ERK phosphorylation." (PMID 30621735, 2019). "To test the relationship between FOXM1 expression and genomic instability using TCGA pan-cancer data, we correlated FOXM1 expression with genomic instability using a recently defined tumor aneuploidy score." (PMID 30795624, 2019). "Further, we also offered evidence that FOXM1 expression was epigenetically regulated by H3K79 methylation, suggesting that FOXM1 and histone methylation are potential targets for cancer therapy." (PMID 30628173, 2019). "Among these genes, CDCA5, FOXM1, KIF15, MCM2, and ZWINT were the most reported genes associated with cancer progression, including EOC." (PMID 31708970, 2019). "Together, these data provide strong evidence that FOXM1c is the highest expressed FOXM1 isoform in both normal tissues and cancer." (PMID 30795624, 2019). "To understand the mechanisms driving increased FOXM1 expression in TCGA pan-cancer, we first focused on FOXM1 copy number alterations." (PMID 30795624, 2019). "This evidence suggested that NFATc2 is functionally linked to FOXM1 and EZH2, two genes known to regulate mesenchymal programs in cancer cells." (PMID 30710146, 2019). "Our study showed overexpression of TOP2A (log2FC = 3.36) and its upstream regulator FOXM1 indicates that both genes are the promising target for anti-cancer therapy for NSCLC." (PMID 31681566, 2019).
cancer (continued). "Increased FOXM1 gene expression and its transcriptional signature are detected in many cancer types." (PMID 30795624, 2019). "We next used the CCLE cancer cell line RNA-seq dataset to compare FOXM1 isoform expression, and again found that FOXM1c showed the highest expression." (PMID 30795624, 2019). "CDK4/6 stabilize and activate FOXM1 by phosphorylation at multiple sites to protect cancer cells from senescence." (PMID 31430272, 2019). "As expected, aneuploidy groups 1, 2, 3 and 5, which show high aneuploidy, were enriched for cancer types with the highest FOXM1 mRNA expression, while group 7, which has low aneuploidy, was enriched for cancer types that show low FOXM1 mRNA expression." (PMID 30795624, 2019). "Angiogenesis is one of the cancer hallmarks in which FOXM1 is mainly involved, inducing matrix metalloproteinase genes as well as VEGFA." (PMID 31311575, 2019). "The data presented here provide useful knowledge for prioritizing the study of FOXM1 function and therapeutic targeting in different types of human cancer." (PMID 30795624, 2019). "FOXM1 is one of the most important oncogenic transcription factors overexpressed in various human cancers." (PMID 30974831, 2019). "The findings presented are also relevant for targeting FOXM1 in cancer, both by revealing vulnerable cancer types and by identifying potential biomarkers for therapeutic studies." (PMID 30795624, 2019). "Owing to the well-known roles in tumor progression, FOXM1 is a potential therapeutic target in many human cancers." (PMID 31072351, 2019). "While other cancer-specific transcripts have been reported for FOXM1, only FOXM1a, -b and -c have been consistently investigated for their expression and function." (PMID 30795624, 2019). "While increased FOXM1 expression is reported in many cancers, we lack an understanding of how FOXM1 copy number, mRNA, and protein expression compare and are associated in pan-cancer." (PMID 30795624, 2019). "We determined the frequency of FOXM1 amplification across the 32 TCGA cancer types using the TCGA Genomic Identification of Significant Targets in Cancer (GISTIC) copy number dataset." (PMID 30795624, 2019). "Different reports describe that FOXM1 is regulated at multiple levels and that its regulation is crucial for its activity and cancer development." (PMID 31311575, 2019). "We demonstrate that HMGA1 and FOXM1 regulate a common gene network, characterized by factors with a clear role in cancer EMT, migration, and angiogenesis, key processes involved in conferring aggressiveness to TNBC." (PMID 31311575, 2019). "Previous studies of FOXM1 isoform expression in cancer have reported that either FOXM1b or FOXM1c has the highest level of expression; however, these studies use different methods and have small sample sizes." (PMID 30795624, 2019). "To address this, we performed a pan-cancer analysis of FOXM1 across 32 TCGA cancer types compared to TCGA normal and GTEx normal tissues." (PMID 30795624, 2019). "Although the isoforms showed obviously different intracellular distributions and action mechanisms, there are few reports investigating the distinct isoforms of FOXM1 in promoting cancer metastasis, a critical step for late‐stage progression." (PMID 30485581, 2019). "Conversely, FOXM1 is an important oncogene that promotes cell transformation, cancer progression and resistance to chemotherapy." (PMID 31727006, 2019). "We also noted that some cancer types that lack FOXM1 amplifications have lower FOXM1 expression (e.g., THCA, PCPG)." (PMID 30795624, 2019). "We utilized genotype-tissue expression (GTEx) normal and The Cancer Genome Atlas (TCGA) tumor data to define FOXM1 expression, including its isoforms, and to determine the genetic alterations that promote FOXM1 expression in cancer." (PMID 30795624, 2019). "It has been concluded that FoxM1 inhibition would significantly impact our treatment of several cancers that express high levels of the protein." (PMID 31134895, 2019).
cancer (continued). "To provide a more comprehensive evaluation of FOXM1 expression in cancer, we compared FOXM1 mRNA expression across 32 TCGA cancer types and in TCGA and GTEx normal tissues, using UCSC TOIL to correct for batch effects and to allow for sample merging." (PMID 30795624, 2019). "FOXM1 is becoming recognised as an important target for cancer therapeutics, and its increased expression has been documented in many diverse tumour types, including colon, breast, prostate, and cervical cancers." (PMID 30728402, 2019). "Previous studies of FOXM1 expression in cancer have used different methods, are limited to small sample sizes, and/or have focused on a single or limited number of cancer types." (PMID 30795624, 2019). "Regarding CRC biology, FOXM1 expression levels have been reported to be correlated with cancer progression, lymph node and liver metastasis and high TNM stages." (PMID 30621735, 2019). "For further analysis, we focused on FOXM1, a transcription factor involved in cell cycle regulation with a pivotal role in cancer initiation and progression." (PMID 31311575, 2019). "Although β-gal activity is a well-established phenotype of cellular senescence in many types of cancer including MM, additional research is warranted to demonstrate the mechanistic link to the FOXM1-Rb pathway." (PMID 30463534, 2018). "FOXM1 is specifically expressed in proliferating cells and is a master regulator of cancer tumorigenesis and metastasis." (PMID 30360388, 2018). "FOXM1 overexpression is involved in the early events of carcinogenesis and plays an important role in cancer growth and metastasis." (PMID 30589909, 2018). "The Forkhead Box M1 (FoxM1) transcription factor, a member of the Fox family of proteins, is highly expressed in a variety of human cancers including HCC." (PMID 29765517, 2018). "Inhibition of FOXM1 in cancer cells leads to decreased cell proliferation and migration, metastasis, angiogenesis, EMT, and drug resistance." (PMID 30208972, 2018). "Consistently in the taxane-resistant DU145-DR and CNE2TR cancer cells, the protein levels of CSC-associated molecules declined with the knockdown of FOXM1." (PMID 29752436, 2018). "FoxM1 is a Forkhead box (Fox) superfamily of transcription factors which is widely expressed in proliferating cells and cancer cells." (PMID 29343703, 2018). "The role of the proto-oncogene forkhead-box M1 (FOXM1) in carcinogenesis and drug resistance development is already well established and has been validated in many cancer types." (PMID 29959570, 2018). "Alternatively, FOXM1 downregulation by stable or transient knockdown using RNAi or by treatment with proteasome inhibitors that target FOXM1 significantly sensitized human cancer cells of different origin to DNA damage-stimulated apoptosis." (PMID 30360388, 2018). "Given the role of FoxM1 in the progression of cell division cycle, it is also overexpressed in majority of cancer patients, making it an important prognostic molecular marker and therapeutic target for several cancer types." (PMID 29343703, 2018). "Emerging evidences reveal that transcription factor Forkhead box M1(FOXM1) is involved in chemoresistance, carcinogenesis, and metastasis, and so suppression of FOXM1 can be a good strategy for cancer therapy." (PMID 30201862, 2018). "Emerging evidence has shown that aberrant upregulation of FoxM1 is seen frequently in various human cancers." (PMID 29423068, 2018). "For example, in cancer cells nucleophosmin (NPM) interacts with FOXM1 and their interaction is required for sustaining the level and nucleus localization of FOXM1." (PMID 30208972, 2018). "Previous studies demonstrated that elevated FoxM1 expression is found in a variety of cancers, including breast, ovarian, colon, liver, pancreatic, gastric and other cancers." (PMID 29707121, 2018). "Previous studies have also reported that FOXO3 can antagonize the functions of FOXM1, which contributes to cancer initiation, progression, and drug resistance." (PMID 30514328, 2018).
cancer (continued). "Previous evidence reveals that overexpression of FOXM1 has been implicated in proliferation, metastasis, epithelial-mesenchymal transition (EMT), chemoresistance, and poor prognosis of cancers." (PMID 30201862, 2018). "Certainly, thiostrepton and casticin induced apoptosis and suppressed cell growth in cancer cells by inhibiting FOXM1." (PMID 30201862, 2018). "Hitherto, expression of FoxM1 had been identified in a number of human cancers, including hematological malignancies and solid tumors." (PMID 29416660, 2018). "Emerging evidences have progressively contributed to our understanding on a central role of FoxM1 in human cancers." (PMID 29416660, 2018). "Targeting FOXM1 sensitizes breast, gastric, and ovarian cancer cells to chemotherapy, as well as lung cancer and B cell leukemia to tyrosine kinase inhibition." (PMID 30089730, 2018). "Recent studies proved that some oncogenes and tumour suppressors, such as PTEN, HIF-1a, Myc, KLF4, FOXM1, and Gas1 regulate glycolysis in cancer cells." (PMID 29463261, 2018). "A plenty of studies, including an insight computational analysis, have demonstrated that elevated FoxM1 expression is a major predictor of adverse outcomes across a variety of human malignancies, indicating the oncogenic activity of FoxM1 in cancer." (PMID 29416660, 2018). "Targeting FoxM1 using thiostrepton, a thiazole antibiotic has been shown to be beneficial in various cancers." (PMID 29707121, 2018). "Although FoxM1 is rarely expressed in quiescent or differentiated cells, its expression is highly elevated in proliferating cells or a variety of cancers." (PMID 29765517, 2018). "Significant progress has been accomplished over the last few years in terms of the pharmacological inhibition of FOXM1 in cancer." (PMID 30208972, 2018). "In most human cancers, FOXM1 is overexpressed, and this indicates a poor prognosis for cancer patients." (PMID 30208972, 2018). "To date, dozens of miRNAs have been found to regulate the proliferation, invasion, migration, senescence, apoptosis, epithelial-mesenchymal transition (EMT), and drug sensitivity of cancer cells through binding to the 3’UTRs of FOXM1 mRNA." (PMID 30208972, 2018). "In summary, all combined results from this study and other groups suggest a novel role for FoxM1 in cancer progression and stem cell features in NPC." (PMID 30416986, 2018). "FOXM1 regulates a variety of processes critical to cancer progression, including tumorigenesis, cell proliferation, metastasis, angiogenesis, and chemoresistance." (PMID 30089730, 2018). "Forkhead family member Forkhead Box M1 (FOXM1) is ubiquitously expressed in a wide range of human cancers and it contributes to several different aspects of oncogenesis." (PMID 29367668, 2018). "Xue and colleagues demonstrated that FoxM1 promoted typical EMT cellular pathway TGF-beta-dependent cancer metastasis via sustained activation of SMAD3/SMAD4." (PMID 29416660, 2018). "FoxM1, a transcription factor with similar expression pattern to Prx II and capability to protect cancer cells from oxidative stress has been identified to govern Prx II overexpression via transcriptionally activating Prx II in HCC cells." (PMID 30177619, 2018). "Actually, overexpression of FoxM1 was also observed in cancer cells migrating into the surroundings and vasculature." (PMID 30416986, 2018). "Conversely, suppression of FoxM1 results in reducing cancer cell proliferation, migration and metastasis." (PMID 30416986, 2018). "In cancer cells, FoxM1 is shown to act downstream of growth signals, such as Ras-mitogen-activated protein kinase pathway or phosphatidylinositol 3-kinase-AKT pathway." (PMID 29765517, 2018). "It has been reported that FOXM1 enhances cancer cell growth through upregulating the cell cycle-related genes cyclin B1 and cyclin D1." (PMID 29552295, 2018). "FOXM1 maintains cancer hallmarks by regulating the expression of target genes at the transcriptional level." (PMID 30208972, 2018).
cancer (continued). "The oncogenic potential of FoxM1 is mainly based on its ability to transcriptionally activate genes that are involved in different facets of cancer development." (PMID 29423068, 2018). "Four cancer specific antigens FOXM1, DEPDC1, KIF20A, and URLC10 were identified based on differential expression in GC samples versus normal tissue based on cDNA arrays and immunohistochemical staining." (PMID 29587677, 2018). "Collectively, these findings confirm a role of FOXM1 in suppressing cellular senescence in cancer cells." (PMID 29180117, 2018). "Due to its potential role as molecular target in cancer therapy, FOXM1 was named the Molecule of the Year in 2010." (PMID 30208972, 2018). "The mode of action of FOXM1 is to facilitate evasion of growth suppressors by cancer cells by activating regulators of cell-cycle progression, anti-oxidant genes, and progression through the EMT phenotype, invasion, and pre-metastatic niche formation." (PMID 30360388, 2018). "Evidence has accumulated regarding the crucial role of FoxM1 in cancer development and progression, suggesting the possible application of FoxM1 as a therapeutic target against cancer." (PMID 29765517, 2018). "Consistently in three pairs of cell lines, FOXM1 protein levels were significantly higher in docetaxel-resistant cells than in parental cancer cells." (PMID 29752436, 2018). "Specifically, tumorigenesis, cancer progression and the development of cancer therapy resistance have often been associated with FOXO3 inactivation or/and FOXM1 overexpression." (PMID 29180117, 2018). "FOXM1 is involved in at least 12 different cancer types, and its overexpression is important for the initiation, progression, and drug resistance of tumors." (PMID 30360388, 2018). "As the FOXM1 signaling network represents a valuable and promising target for further cancer treatment personalization, we here investigate its clinical impact in three cohorts with a total of 737 NMIBC patients." (PMID 29959570, 2018). "Prx II regulates stemness-associated characteristics of cancers via several pathways, mainly including VEGF/VEGFR/STAT3, Ras/FoxM1, JNK, Wnt/β-Catenin, Hedgehog and androgen (AR)/androgen receptor signaling." (PMID 30177619, 2018). "Interest in FOXM1 dysregulation and its impact on cancer management has been maintained in recent years." (PMID 30360388, 2018). "We found that the injection of FoxM1-overexpressing cancer cells into nude mice yielded larger tumors than in the control groups." (PMID 30416986, 2018). "A comprehensive understanding of FOXM1 regulation will provide novel insight for cancer and other diseases in which FOXM1 plays a major role." (PMID 30208972, 2018). "Using the gene microarray and RNAi mediated silencing approach; we have also identified a key molecular target of hsa-miR-6852 (miR-SX4) as FoxM1 that is involved in mediating the anti-cancer effects of miR-SX4." (PMID 29343703, 2018). "Accordingly, dysregulation of FOXO3 and/or FOXM1 is responsible for the acquisition of multi-drug resistance in cancer cells." (PMID 29180117, 2018). "Because of its key role in cancer development, FOXM1 emerged as an important and relevant candidate of therapeutic intervention." (PMID 29367668, 2018). "In the light of the studies that pinpoint FOXM1 as an important pan-cancer gene, several labs are undertaken efforts to identify drugs that target FOXM1." (PMID 30504901, 2018). "Several studies have shown that the transcriptional activity of FOXM1 is more predictive than its mRNA expression in cancers." (PMID 29100329, 2017). "Compared with the RNA interference of FOXM1 in cancer cells, M-FOXM1 Apt repressed cell proliferation and the expression of FOXM1 target genes without changing FOXM1 levels." (PMID 28358012, 2017). "Targeting FoxM1 is a good strategy for cancer therapeutics, because FoxM1 also regulates Wnt/β-catenin pathway." (PMID 28378765, 2017).